MYD88 (MYD88 innate immune signal transduction adaptor)
Diseases named in the same sentence as MYD88 in open-access papers (continued):
Sharing a sentence is not in itself a finding about the gene and the disease.
atherosclerosis (continued). "Indeed, mice deficient in TLR4, TLR2 and MyD88 all have reduced atherosclerosis which establishes that TLR-dependent pathways contribute to disease development." (PMID 18787704, 2008). "Taken together, our observed findings suggest that the involvement of core genes related to the risk of atherosclerosis might be a critical metric in ubiquitin-mediated proteolysis, Toll-like receptor, and MyD88: MAL (TIRAP) cascades and a beneficial tool for diagnosis and targeted therapy." (PMID 32760426, 2020). "On the ex vivo cultures of cells isolated from human atherosclerosis plaques the production of several cytokines, inflammatory mediators and metalloproteinases was significantly reduced with dnMyD88 (MyD88 aa 53-296 P56N) where the P56N mutation in the DD of MyD88 is unable to form DD homodimers." (PMID 23305364, 2012). "For instance, MyD88 in innate cells can lead to atherosclerosis, while MyD88 in adaptive cells confers protection." (PMID 40877572, 2025). "MyD88 knockout macrophages have demonstrated reduced plaque formation indicating their potential use for studying atherosclerosis protection." (PMID 39247623, 2024). "One critical factor in the initiation and progression of atherosclerosis is the release of inflammatory factors and cytokines produced by the MyD88 upon the activation of toll-like receptor 4 (TLR4)." (PMID 39247623, 2024). "Overall, this model for atherosclerosis protection can further enhance our understanding of the specific role of MyD88 signaling in the development and progression of atherosclerosis." (PMID 39247623, 2024). "This study successfully identified key genes associated with EndMT-related atherosclerosis, such as CD68, TLR2, MYD88, IRF7, STAT1, and IL1B, all of which demonstrate substantial diagnostic potential for detecting atherosclerotic plaques." (PMID 38268851, 2023). "In conclusion, the results suggest that Mettl14 can regulate the function of macrophages in atherosclerosis via Myd88/IL-6 in vivo." (PMID 35598196, 2022). "The mechanism by which circ-RELL1 promotes the development of atherosclerosis is achieved by a ceRNA regulating the miR-6873-3p/MyD88/NF-κB axis, while circ-ANRIL increases the number of inflammatory factors to promote atherosclerosis." (PMID 36393967, 2022). "Polydatin synergizes with P. sibiricum polysaccharides in preventing the development of atherosclerosis in ApoE–/– mice by inhibiting the TLR4/MyD88/NF-κB signaling pathway." (PMID 35845572, 2022). "It has been shown that ABCA1 expression in macrophages can protect against atherosclerosis through reduction in cholesterol in macrophage plasma membrane and lipid raft content, which suppresses proinflammatory MyD88-dependent signaling pathways." (PMID 36363591, 2022). "This study identified that rSj-Cys stimulated Treg and M2 macrophages to secrete regulatory cytokines IL-10 and TGF-β that inhibit oxidized lipid-induced inflammation and atherosclerosis through inhibiting the TLR2/Myd88 pathway." (PMID 34901005, 2021). "Following coronavirus infection, the NF-kB pathway is activated via the MyD88 pathway, and increased transcription of NF-kB-dependent genes has implications for cardiomyopathy, atherosclerosis, and COVID-19 severity." (PMID 34071557, 2021). "These highlighted the potential role of TLRs/MyD88 cascade in the Tregs response and progression of atherosclerosis." (PMID 34095251, 2021). "Cytokine storm involved in heart failure, myocardial fibrosis, atherosclerosis and cardiotoxicity induced by anticancer drugs is induced by overexpression of MyD88 and NLRP3 inflammasome." (PMID 34178667, 2021). "More importantly, MyD88-dependent TLR signaling was shown to be essential in the suppression of atherosclerosis mediated by Tregs." (PMID 34095251, 2021).
atherosclerosis (continued). "Apolipoprotein E (ApoE)-deficient mice are prone to high-fat diet-induced atherosclerosis, which is reduced in additional TLR4-deficiency or MyD88-deficiency, indicating an important role of TLR4/MyD88 signaling in atherosclerosis." (PMID 32391019, 2020). "With the chronic atherosclerosis model, TRAM, or TRIF deficiency, instead of MyD88 deficiency, was found to have reduced inflammation and atherosclerosis progression." (PMID 27891130, 2016). "Future studies will be required employing mice in which key inflammatory signal transducers, such as MyD88, are conditionally deleted within vascular cells to determine the role such pathways play in age‐enhanced atherosclerosis." (PMID 27135421, 2016). "The reduction of atherosclerosis in mice treated with these constructs was associated with a decrease in both TLR4 and MyD88 contents." (PMID 25830298, 2015). "And there was evidence indicating that MyD88−/−ApoE−/− mice displayed a 57% reduction in the extent of atherosclerosis." (PMID 26257462, 2015). "Both IL1 and IL18 signal through MyD88, and their absence in experimental mouse atherosclerosis also has the effect of limiting atherosclerosis development." (PMID 21526997, 2011). "In a functional human atherosclerosis study, a significant reduction of pro-inflammatory cytokines and MMPs was found after MyD88 inhibition." (PMID 21526997, 2011). "MyD88 (myeloid differentiation primary response 88) is an adaptor protein that plays a significant role in initiating and amplifying the immune response in atherosclerosis by inducing signalling from multiple receptors at the plasma membrane and endosomes." (PMID 39247623, 2024). "Additionally, MYD88-dependent activation in aortic endothelial cells increases PCSK9 (proprotein convertase subtilisin/kexin type 9) expression, suggesting a role for MYD88 in promoting atherosclerosis by affecting endothelial lipid processing." (PMID 38610757, 2024). "Consequently, CD11c-selective depletion of Myd88 exacerbates atherosclerosis, suggesting that the overall effect of MYD88-mediated DC activation and maturation is atheroprotective, primarily through the promotion of atheroprotective Treg cells." (PMID 38397127, 2024). "Furthermore, studies have shown that TLR-2 plays a significant role in driving inflammation in human atherosclerosis through a signaling adaptor called MyD88." (PMID 38002294, 2023). "In order to assess whether MYD88-mediated signaling pathways are responsible for the progression of atherosclerosis and inflammation, we performed an analysis of the correlation coefficients between MYD88 and all other biomarkers in both aortas." (PMID 37298199, 2023). "Based on these, we propose the hypothesis that QB can reduce the inflammatory response and delay disease progression in SLE combined with atherosclerosis by inhibiting the HMGB1/TLR4/MyD88 pathway." (PMID 35571092, 2022). "In addition, the MyD88 inhibitor LM9 has been shown to prevent the pathogenesis of atherosclerosis, accompanied by reduced vascular inflammation and oxidative stress in ApoE−/− mice fed upon a high-fat diet." (PMID 35795853, 2022). "As a crucial downstream target shared by most TLRs, the MyD88 signaling could enhance immunity and promote plaque growth and might regulate plaque stability in atherosclerosis." (PMID 34095251, 2021). "TLR2/Myd88 signaling pathway plays an important role in the pathogenesis of atherosclerosis." (PMID 34901005, 2021). "Interestingly, MyD88-mediated signaling plays a prominent role in the development of human atherosclerosis and matrix degradation." (PMID 32760426, 2020). "Collectively, these results indicate that inactivation of TLR4/MyD88-dependent signaling strongly inhibits development of atherosclerosis and promotes a more stable plaque phenotype, mainly by reducing inflammatory molecule release as a consequence of NF-κB inactivation." (PMID 25757594, 2015).
atherosclerosis (continued). "Additionally, a previous study documented that common mechanisms of signaling via TLR2, TLR4 and MyD88 link stimulation by multiple pathogens and endogenous ligands to atherosclerosis progression." (PMID 25010102, 2014). "Its function is illustrated by the effect of knocking out the MyD88 gene in atherosclerosis." (PMID 23880853, 2013). "TLR2, TLR4 and MyD88 have an important role in the development of atherosclerosis characterized by the accumulation of proinflammatory cytokines, chemokines and matrix metalloproteinases (MMPs) mediated by several different cell types in the endothelium of the artery lumen." (PMID 23305364, 2012). "Thus, remodeling of these pathways also by alternative, or adjuvant venues to knocking out the MyD88 could play a crucial role in the re-programming of macrophages to prevent the formation of atheroma plaques and advancement of atherosclerosis disease." (PMID 39247623, 2024). "Any genetic mutation within this pathway, especially in key genes like TLR4 and MyD88, could potentially alter the action of other components of the pathway so as to influence inflammatory reactions in the pathogenesis and progression of atherosclerosis." (PMID 26959040, 2016). "The blockage of MyD88 is certainly an interesting strategy for the treatment of atherosclerosis, however, due to the broad role of the adaptor molecule in TLR signalling, it could be preferential to target individual TLRs to achieve more specific therapeutic outcomes." (PMID 23880853, 2013). "Macrophages isolated from MyD88−/− mice exhibited reduced activation, lipid accumulation and foam cell formation in response to ox-LDL treatment, a key factor in atherosclerosis." (PMID 39247623, 2024). "Recent studies indicate that the TLR4/MyD88/NLRP3 pyroptosis signaling pathway plays a key role in the occurrence and development of cancer, heart failure, and atherosclerosis." (PMID 36733418, 2023). "Previous studies have shown that PM2.5 promotes plaque vulnerability at different stages of atherosclerosis, the formation of foam cells, and lung injury and exacerbates allergic inflammation in the murine lung via the TLR4/MyD88/NFκB pathway." (PMID 35795853, 2022). "Accumulating evidence from basic research shows that PCSK9 promotes vascular inflammation through upregulating classical pro-inflammatory pathways involved in atherosclerosis, such as TLR4/MyD88/NF-κB and NLRP3 inflammasomes." (PMID 36291690, 2022). "In other studies, it has been shown that atorvastatin has an anti-inflammatory effect on atherosclerosis through TLR4 and the MYD88-dependent pathway in a dose- and time-dependent manner." (PMID 32378144, 2021). "Some scholars have shown that downstream molecules such as MyD88 and TRAF6 also have key effects on atherosclerosis." (PMID 32849545, 2020). "In human atheroma cell cultures blockade of TLR2 and MyD88 inhibits NF-κB activation and matrix metalloproteinase (MMP) production, suggesting that MyD88-mediated TLR2 signaling contributes to human atherosclerosis." (PMID 30225265, 2018). "Previous studies showed that activated TLR4/MyD88 upregulated NOX4 expression in LPS-activated cells and lead to atherosclerosis." (PMID 27891092, 2016). "Minimally modified LDL (a subtype of oxLDL that is essential for atherosclerosis) induces ROS production and macrophage cytoskeletal rearrangements in a TLR4 dependent and MyD88-independent manner." (PMID 27795867, 2016). "A different story unfolded from TLR3 in atherosclerosis—an endosomal TLR that signals via TRIF and is MyD88-independent." (PMID 23880853, 2013). "In humans, studies of atheroma cell cultures revealed that blockade of TLR2 and MyD88 inhibits NF-κB activation and matrix metalloproteinase (MMP) production, suggesting that MyD88-mediated TLR2 signalling contributes to human atherosclerosis." (PMID 23880853, 2013).
atherosclerosis (continued). "In addition, Jieduquyuziyin prescription was also effective in alleviating atherosclerosis symptoms, mainly by regulating cholesterol efflux and inhibiting TLR9/MyD88 activation." (PMID 38952541, 2024). "While the deletion of Myd88 expression could suppress the inflammatory response, Myd88 has become a novel therapeutic target for many diseases related to inflammation, such as chronic obstructive pulmonary disease (COPD) and atherosclerosis." (PMID 37175545, 2023). "We noted a significant upregulation between MYD88 and CCL20 (G60); IFNβ (G90); NF-kB, IL18 (G120); NF-kB, CCR2, IL1b, IL18 (GF120); and CCR2 (GR120) in the thoracic aorta during the inflammatory process of atherosclerosis." (PMID 37298199, 2023). "A novel MyD88 inhibitor (LM9) can significantly reduce oxidative stress and vascular inflammation in mice, thus its inhibition can be considered as an effective target for the treatment of atherosclerosis." (PMID 35845572, 2022). "Although the exact mechanism has not been fully elucidated, the HMGB1/TLR4/MyD88 signaling pathway appears to be a new target for SLE combined with atherosclerosis treatment." (PMID 35571092, 2022). "TLR signaling is expressed through the adapter protein MyD88 and the lack of MyD88 prevents from vascular complications and atherosclerosis." (PMID 33802371, 2021). "Our results indicated that C8:0 reduced body fat, improved the lipid profiles, suppressed inflammatory cytokine production, downregulated aortic TLR4, MyD88, NF-κB, TNF-α, IKKα, and IKKβ mRNA expression, and alleviated atherosclerosis in the apoE−/− mice (P < 0.05)." (PMID 31182969, 2019).
breast cancer (66 papers, 2010 to 2026). A primary or metastatic malignant neoplasm involving the breast. "Subsequent research endeavors should be directed towards elucidating the intricate mechanisms underlying MyD88's role in breast cancer progression, as well as harnessing its potential for devising innovative, precision-targeted therapeutic approaches." (PMID 39744584, 2025). "We discovered that elevated MyD88 expression is associated with improved patient outcomes and is linked to the immunological landscape of breast cancer, including immune cell infiltration and the expression of immune checkpoint genes." (PMID 39744584, 2025). "Subsequently, we explored the association between MyD88 and the carcinogenic pathways implicated in breast cancer." (PMID 39744584, 2025). "Collectively, these observations underscore the pivotal role that MyD88 plays in the oncogenic mechanisms linked to breast cancer development." (PMID 39744584, 2025). "Nevertheless, in-depth research is essential to unveil the precise mechanisms underlying the diverse roles of MyD88 in breast cancer." (PMID 38347830, 2024). "A multitude of studies has revealed a profound association between MyD88 expression levels and the severity and prognostication of breast cancer." (PMID 38347830, 2024). "Further research is required to elucidate the potential mechanisms underlying MyD88-mediated drug resistance in breast cancer and other cancer types, as well as to explore therapeutic intervention methods." (PMID 38347830, 2024). "MyD88 exerts a significant impact on drug resistance in breast cancer cells and is recognized as a key player associated with paclitaxel (PTX) resistance." (PMID 38347830, 2024). "Previous studies have shown that TLR4/MyD88/NF-κB pathway is linked to the inflammatory response in hepatocellular carcinoma, breast cancer, and tumor-associated macrophages (TAMs) on Ishikawa cells." (PMID 33849528, 2021). "Our preliminary study showed that MyD88 was implicated in PTX sensitivity in breast cancer and that UA increased the expression of miR-149-5p and subsequently decreased the expression of MyD88." (PMID 31259152, 2019). "Furthermore, our analysis of the immune microenvironment indicated that MyD88 expression is linked to the immunological landscape of breast cancer." (PMID 39744584, 2025). "This association underscores MyD88's potential as a prognostic biomarker in breast cancer." (PMID 39744584, 2025). "Notably, the expression level of MyD88 level closely associates with disease severity, prognosis, and staging of breast cancer." (PMID 38347830, 2024). "Additionally, several studies have shown that MyD88 is associated with clinicopathological features, such as histological subtypes of ovarian cancer, cell metastasis of breast cancer, and lymphatic metastasis." (PMID 38785969, 2024). "MyD88, therefore, emerges as a potential diagnostic and therapeutic target in breast cancer." (PMID 38347830, 2024). "In addition, AGAP2-AS1 regulates trastuzumab resistance by targeting MYD88 (encoding MYD88 innate immune signal transduction adaptor) in breast cancer." (PMID 32960785, 2020). "TLR4-MyD88 signaling pathway activation or MyD88 activation alone may be a risk factor for poor prognosis in breast cancer." (PMID 25360699, 2014). "Finally, MyD88 overexpression alone upregulated the levels of 5-LO and 12-LO, as well as the quantity of BLT2 ligands, indicating that the MyD88-5-LO/12-LO-LTB4/12(S)-HETE-linked pathway lies upstream of BLT2 in the LPS-potentiated invasiveness in breast cancer cells." (PMID 25691060, 2015). "Our work provides new insight into the development/progression of inflammation and breast cancer, suggesting that activation of the TLR4-MyD88 signaling pathway or MyD88 alone may be risk factors for a poor breast cancer prognosis and may be novel targets for the development of biomodulators." (PMID 25360699, 2014).